ELMO3 (engulfment and cell motility 3)
Description:
Involved in cytoskeletal rearrangements required for phagocytosis of apoptotic cells and cell motility. Acts in association with DOCK1 and CRK. Was initially proposed to be required in complex with DOCK1 to activate Rac Rho small GTPases. May enhance the guanine nucleotide exchange factor (GEF) activity of DOCK1 (By similarity).
Synonyms: FLJ13824; CED12; ELMO-3; CED-12
Tractability: Antibody: the Human Protein Atlas places it where antibodies can reach. PROTAC: ubiquitination databases record sites on it.
Gene: Protein-coding gene on chromosome 16 (67,199,111 to 67,204,029, forward strand). Ensembl gene ENSG00000102890.
Subcellular location: Cytoplasm
Subcellular location (Human Protein Atlas): Cell Junctions; Plasma membrane
Gene Ontology:
Molecular function: protein binding; guanyl-nucleotide exchange factor activity
Biological process: actin filament organization; cell motility; regulation of vasculogenesis
Cellular component: cytoplasm
Genetic constraint (gnomAD): Loss-of-function variants: 81 observed, 89.17 expected, observed/expected ratio (o/e) 0.91, 90% interval 0.76 to 1.09. The upper end of that interval is the gene's LOEUF score, 1.09, which puts it in group 4 of 6, group 1 being the genes least tolerant of losing a copy. Missense variants: 958 observed, 988.92 expected, observed/expected ratio (o/e) 0.97, 90% interval 0.92 to 1.02. Synonymous variants: 406 observed, 408.89 expected, observed/expected ratio (o/e) 0.99, 90% interval 0.92 to 1.08.
Homologues: Orthologues: chimpanzee ELMO3 (99% identical), macaque ELMO3 (98% identical), pig ELMO3 (93% identical), dog ELMO3 (92% identical), guinea pig ELMO3 (92% identical), rabbit ELMO3 (92% identical), mouse Elmo3 (91% identical), rat Elmo3 (91% identical), zebrafish elmo3 (63% identical), tropical clawed frog elmo3 (60% identical). Paralogues in human: ELMO1 (52% identical), ELMO2 (50% identical), ELMOD1 (10% identical), ELMOD3 (9% identical), ELMOD2 (8% identical).
Diseases named in the same sentence as ELMO3 in open-access papers:
ELMO3 is named in the same sentence as 28 diseases in open-access papers, as found by Europe PMC text mining. Sharing a sentence is not in itself a finding about the gene and the disease. The quoted sentences say what the papers report.
lung carcinoma (13 papers, 2014 to 2024). "The results of studies in lung cancer suggest that ELMO3 protein is a potential diagnostic and prognostic marker for NSCLC." (PMID 31134158, 2019). "Hypomethylation and increased expression of the putative oncogene ELMO3 are associated with lung cancer development and metastases formation." (PMID 25146334, 2014). "High expression of ELMO3 have been linked with poor prognosis in lung cancer, head and neck squamous cell carcinoma, and laryngeal cancer, and we have previously shown that methylation levels of the ELMO3 promoter is inversely correlated with expression of the gene." (PMID 29495584, 2018). "For instance, hypomethylation has been observed in the oncogenes AQP1, LINE-1, and ELMO3 in salivary gland adenoid cystic carcinoma, colorectal cancer, and lung cancer, respectively." (PMID 38399367, 2024). "Other authors also revealed that parecoxib can suppress metastasis by reducing the expression of engulfment and cell motility 3 (ELMO3) in lung cancer." (PMID 39062099, 2024). "A hypomethylation status has been reported for several oncogenes, including AQP1 in salivary gland carcinoma, LINE-1 in colorectal cancer, and ELMO3 in lung cancer." (PMID 37175004, 2023). "ELMO3 has also been reported to participate in events related to metastasis in several types of cancer, including lung cancer, colorectal cancer, and squamous-cell carcinoma of the head and neck." (PMID 32292657, 2020). "ELMO3, however, is only reported to be highly expressed in early glottic cancer, lung cancer and colorectal cancer." (PMID 31134158, 2019). "Our results demonstrate that down regulation of ELMO3 suppressed growth and metastasis of lung cancer by inhibiting EMT." (PMID 31134158, 2019). "The expression of ELMO3 has only been reported in lung cancer with distant metastasis and colon cancer cell lines." (PMID 27999268, 2016). "In lung cancer, the overexpression of ELMO3 coincides with the hypomethylation of its promoter CpG island." (PMID 27999268, 2016). "This study has established a new therapeutic target ELMO3 for lung cancer treatment." (PMID 31134158, 2019). "Parecoxib could inhibit the growth, adhesion, EMT and metastasis of lung cancer cells by downregulating ELMO3." (PMID 31134158, 2019). "Parecoxib could reduce ELMO3 expression and suppress growth and metastasis of lung cancer, which might be a useful chemotherapeutic agent for inhibiting metastasis and recurrence of NSCLC." (PMID 31134158, 2019). "ELMO3 has not previously been described as being implicated in lung cancer development, and studies of its expression or regulation in primary patient samples have not previously been reported." (PMID 25594031, 2014). "ELMO3, in coordination with CDX2 plays a role in cellular migration in the intestine and during metastasis in lung cancer." (PMID 34178034, 2021).
colorectal cancer (10 papers, 2016 to 2024). A primary or metastatic malignant neoplasm that affects the colon or rectum. "Moreover, loss of ELMO3 is implicated in lymphatic metastasis in colorectal cancer, and in metastatic capacity in PDAC." (PMID 38902676, 2024). "Interestingly, ELMO family members such as ELMO1 and ELMO3 have been implicated in a variety of malignant cancers, such as glioma, breast cancer, colorectal cancer, hepatocellular carcinoma, and non-small-cell lung carcinoma." (PMID 32292657, 2020). "In colorectal cancer Caco-2 cells, the activity of the ELMO3 promoter can be regulated by caudal-related homeobox transcription factor 2 (CDX2), which interacts with SP1." (PMID 30345300, 2018). "ELMO3 (Engulfment and Motility 3) is involved in induction of cell proliferation, invasion and metastasis in colorectal cancer cells." (PMID 29854292, 2018). "This is also in agreement with our previous report on colorectal cancer, in which silencing ELMO3 significantly induced G1 cell cycle arrest." (PMID 30345300, 2018). "A further investigation is necessary to explore how ELMO3 leads to colorectal cancer cell migration through regulating actin polymerization and the cytoskeleton." (PMID 27999268, 2016). "The study found that ELMO3 knockdown inhibited colorectal cancer growth and metastasis." (PMID 31134158, 2019). "In this study, we hypothesized that ELMO3 could play a key role in the cell growth, invasion and metastasis of colorectal cancer." (PMID 27999268, 2016). "To elucidate its role in the development and progression of colorectal cancer (CRC), we examined the expression of ELMO3 in 45 cases of paired CRC tumor tissues and adjacent normal tissues." (PMID 27999268, 2016). "The results of wound-healing and Transwell assays revealed that knockdown of ELMO3 could inhibit the invasion and migration of SGC7901 and BGC823 cells, which is consistent with previous studies in colorectal cancer." (PMID 30345300, 2018). "Furthermore, ELMO3 was expressed more highly in CRC tumor tissues from patients with lymphatic node metastasis than that in CRC tumor tissues from patients without lymphatic node metastasis, which shows that ELMO3 is possibly involved in colorectal cancer metastasis." (PMID 27999268, 2016).
non-small cell lung carcinoma (5 papers, 2018 to 2026). A group of at least three distinct histological types of lung cancer, including non-small cell squamous cell carcinoma, adenocarcinoma, and large cell carcinoma. "In addition, ELMO3 positive/higher expression is associated with poor overall survival in non-small cell lung cancer and head and neck cancer, as well as in breast cancer, corroborating its role as an oncogene." (PMID 29854292, 2018). "In non-small-cell lung cancer, the high expression level of ELMO3 coincides with low methylation levels of its promoter region, contributing to the formation of metastases." (PMID 30345300, 2018). "In non-small-cell lung cancer, the ELMO3 mRNA transcript level is significantly upregulated in patients' cancer tissues and serum compared with matched adjacent tissues." (PMID 30345300, 2018). "Studies in non-small cell lung cancer tumors showed that ELMO3 expression is higher in patients with metastasis than in normal lung tissue and patients without metastasis indicating a poor prognosis for patients with high ELMO3 expression." (PMID 30374620, 2019). "Furthermore, in non-small-cell lung cancer, high expression of ELMO3 is found in combination with low methylation levels of its promoter region, which are associated with the formation of metastases." (PMID 30345300, 2018). "Recently, ELMO3 has been described as a negative prognostic biomarker in non-small cell lung cancer, head and neck squamous carcinoma and T1 laryngeal cancer." (PMID 30374620, 2019).
breast carcinoma (3 papers, 2016 to 2018). "Whether ELMO3 in gastric cancer cells serves a similar role as ELMO2 in breast cancer cells needs further investigation." (PMID 30345300, 2018). "However, because no ELMO3 expression was detected in breast cancer, it is difficult to speculate whether ELMO3 acts through a similar mechanism in regulating colorectal cell growth." (PMID 27999268, 2016).
deafness (3 papers, 2022 to 2023). An inherited or acquired condition characterized by the complete loss of the ability to hear from one or both ears. "There were 18 genes linked only to Metabolic hearing loss (including four deafness genes: DMD, DUOX2, CELSR1 and ELMO3) and 54 genes linked only to Sensory hearing loss (including four deafness genes: ARHGAP21, LMO7, UBE3B and ADGRV1)." (PMID 38011198, 2023). "Twenty-five genes were present in both male and female hearing difficulty high variant load lists, including seven deafness genes (CLIC5, MYH14, COL9A3, ELMO3, FSCN2, GJB2, SLC26A5)." (PMID 35761239, 2022). "PKHD1L1, DUOX2, CELSR1, ELMO3, ARHGAP21, LMO7 and UBE3B are all defined as deafness genes through work on the mouse orthologues." (PMID 37163093, 2023).
head and neck squamous cell carcinoma (3 papers, 2018 to 2019). A squamous cell carcinoma that arises from any of the following anatomic sites: lip and oral cavity, nasal cavity, paranasal sinuses, pharynx, larynx, and salivary glands. "Furthermore, investigations in head and neck squamous cell carcinomas showed that ELMO3 expression correlates with a decreased overall survival (OS) and disease-free survival (DFS)." (PMID 30374620, 2019).
glioblastoma (2 papers, 2018). The most malignant astrocytic tumor (WHO grade IV). "We found that the methylation levels of ELMO1 and ELMO2 were generally low, whereas ELMO3 methylation levels were high, in the glioblastoma samples." (PMID 29495584, 2018). "On the contrary, less is known about the roles of ELMO2 and ELMO3 in glioblastoma." (PMID 29495584, 2018). "Among 121 included glioblastoma patients, successful pyrosequencing results were obtained from 113, 104, and 119 of the patient samples for ELMO1, ELMO2, and ELMO3, respectively." (PMID 29495584, 2018). "Since glioblastoma patients receiving Stupp’s regimen having an unmethylated MGMT promoter present shorter PFS and OS, this may also explain the shorter PFS of patients with ELMO3 hypomethylation." (PMID 29495584, 2018).
lymph node metastasis (2 papers, 2016 to 2018). "Several previous studies report ELMO3 augmented expression parallels increased lymph node metastasis." (PMID 30345300, 2018). "More evidence was acquired by IHC analysis, which revealed that the expression of ELMO3 was positively correlated with the pathologic differentiation degree, depth of invasion, lymph node metastasis, distant metastasis and TNM stage." (PMID 27999268, 2016). "Furthermore, for those GC patients with lymph node metastasis, the protein level of ELMO3 was markedly higher in cancer tissue than in lymph node metastasis-free patients (P = 0.017)." (PMID 30345300, 2018). "Moreover, for those CRC patients with lymph node metastasis, the mRNA level of ELMO3 in CRC tissues was markedly higher than that in CRC tissues from patients without lymph node metastasis (p = 0.000)." (PMID 27999268, 2016). "Stronger staining of ELMO3 was detected in cancer cells with lymph node metastasis than in cancer cells without lymph node metastasis (p = 0.003)." (PMID 27999268, 2016). "Furthermore, the protein level of ELMO3 in patients with lymph node metastasis was also significantly higher than that in patients without lymph node metastasis (p = 0.011)." (PMID 27999268, 2016).
adenoid cystic carcinoma (1 paper, 2019). A malignant tumor arising from the epithelial cells. "Beside ELMO3 expression, adenoid cystic carcinoma (p = .033) and adenocarcinoma (p = .018) were associated with reduced DFS rates in univariate analysis." (PMID 30374620, 2019). "Adenoid cystic carcinoma: In adenoid cystic carcinoma, 13 (52%) of 25 patients had a high ELMO3 staining and 12 (48%) patients had a low ELMO3 staining." (PMID 30374620, 2019).
basal cell adenocarcinoma (1 paper, 2019). "Basal cell adenocarcinoma: In basal cell adenocarcinoma 100% (one of one) of the samples showed high ELMO3 staining." (PMID 30374620, 2019).
Clear cell carcinoma (1 paper, 2019). "Clear cell carcinoma: High ELMO3 staining was detected in 100% (one of one) of the patients with clear cell carcinoma." (PMID 30374620, 2019).
gastric cancer (1 paper, 2018). A primary or metastatic malignant neoplasm involving the stomach. "The expression level of ELMO3 in gastric cancer tissues and cell lines was measured by means of real-time quantitative PCR (qPCR) and Western blot analysis." (PMID 30345300, 2018). "The present study was conducted to investigate the function and role of ELMO3 in gastric cancer (GC) progression." (PMID 30345300, 2018). "We further examined the expression of ELMO3 in five gastric cancer cell lines, including SGC7901, BGC823, MGC803, AGS, and MKN74, and in one normal gastric epithelial cell line, Ges-1." (PMID 30345300, 2018). "ELMO3 is expected to be a new predictive biomarker for diagnosis and serves as a potential target for the treatment of gastric cancer." (PMID 30345300, 2018). "RNA interference was used to inhibit ELMO3 expression in gastric cancer cells." (PMID 30345300, 2018). "Therefore, we compared the expression level of ELMO3 in gastric cancer tissue with that in matched adjacent normal tissues." (PMID 30345300, 2018). "Currently, there are no reports about the function and molecular regulation of ELMO3 in gastric cancer." (PMID 30345300, 2018).
intestinal cancer (1 paper, 2019). "Studies in human intestinal cancer cell lines showed that homeobox protein CDX2 plays a role in the transcriptional regulation of intestine-specific expression of ELMO3." (PMID 30374620, 2019). "In vitro, ELMO3 was also detected in human intestinal cancer cell lines." (PMID 30374620, 2019).
Lewis lung carcinoma (1 paper, 2019). "Moreover, knockdown of ELMO3 suppressed the epithelial-mesenchymal transition (EMT), adhesion, and metastasis of Lewis lung carcinoma (LLC) cells." (PMID 31134158, 2019).
minor salivary gland carcinoma (1 paper, 2019). A carcinoma that arises from the minor salivary glands. "The aim of this study was to investigate the expression of ELMO3 in patients with minor salivary gland carcinoma using immunohistochemical staining." (PMID 30374620, 2019). "The aim of this study was to evaluate ELMO3 expression in patients with minor salivary gland carcinoma." (PMID 30374620, 2019). "In this study the expression pattern of ELMO3 in minor salivary gland carcinoma has been investigated." (PMID 30374620, 2019). "Furthermore, we found a statistically significant negative effect of high ELMO3 expression in terms of DFS in patients with minor salivary gland carcinoma." (PMID 30374620, 2019). "Therefore we think that ELMO3 might serve as a negative prognostic marker in patients with minor salivary gland cancer." (PMID 30374620, 2019).
mucoepidermoid carcinoma (1 paper, 2019). A carcinoma morphologically characterized the presence of cuboidal mucous cells, goblet-like mucous cells, squamoid cells, cystic changes, and a fibrotic stromal formation. "In intermediate grade mucoepidermoid carcinoma samples two (100%) of two samples showed low ELMO3 expression." (PMID 30374620, 2019). "Mucoepidermoid carcinoma: High ELMO3 expression was detected in two (28.6%) of seven low grade mucoepidermoid carcinoma samples and low ELMO3 expression in five (71.4%) of these samples." (PMID 30374620, 2019).